SUPT3H (SPT3 homolog, SAGA and STAGA complex component)
Description:
Probable transcriptional activator.
Synonyms: SPT3; SPT3L
Tractability: PROTAC: UniProt records ubiquitination sites on it; ubiquitination databases record sites on it.
Gene: Protein-coding gene on chromosome 6 (44,809,317 to 45,377,953, reverse strand). Ensembl gene ENSG00000196284.
Subcellular location: Nucleus
Subcellular location (Human Protein Atlas): Nucleoplasm
Pathways (Reactome):
Chromatin organization: HATs acetylate histones
Gene Ontology:
Molecular function: transcription coactivator activity; protein heterodimerization activity
Biological process: regulation of transcription by RNA polymerase II; positive regulation of DNA-templated transcription; regulation of DNA repair; regulation of DNA-templated transcription; regulation of RNA splicing; transcription by RNA polymerase II
Cellular component: nucleoplasm; nucleus; SAGA complex; transcription factor TFTC complex
Genetic constraint (gnomAD): Loss-of-function variants: 17 observed, 19 expected, observed/expected ratio (o/e) 0.89, 90% interval 0.61 to 1.34. The upper end of that interval is the gene's LOEUF score, 1.34, which puts it in group 5 of 6, group 1 being the genes least tolerant of losing a copy. Missense variants: 237 observed, 238.16 expected, observed/expected ratio (o/e) 1, 90% interval 0.89 to 1.11. Synonymous variants: 70 observed, 78.04 expected, observed/expected ratio (o/e) 0.9, 90% interval 0.74 to 1.09.
Homologues: Orthologues: chimpanzee SUPT3H (99% identical), dog SUPT3H (97% identical), pig SUPT3H (92% identical), mouse Supt3 (92% identical), macaque SUPT3H (91% identical), rat Supt3h (90% identical), rabbit SUPT3H (83% identical), guinea pig SUPT3H (80% identical), tropical clawed frog supt3h (79% identical), zebrafish supt3h (73% identical), Drosophila melanogaster Spt3 (30% identical). Paralogues in human: TAF13 (9% identical).
Diseases named in the same sentence as SUPT3H in open-access papers:
SUPT3H is named in the same sentence as 6 diseases in open-access papers, as found by Europe PMC text mining. Sharing a sentence is not in itself a finding about the gene and the disease. The quoted sentences say what the papers report.
osteoarthritis (2 papers, 2022 to 2024). A noninflammatory degenerative joint disease occurring chiefly in older persons, characterized by degeneration of the articular cartilage, hypertrophy of bone at the margins and changes in the synovial membrane. "Several osteoarthritis-associated SNVs map to genes encoding post-translational modifiers of histone proteins, including the histone methyltransferase gene DOT1L and the histone acetylation and de-ubiquitinase gene SUPT3H." (PMID 38430365, 2024). "SUPT3H and RUNX2 were found to be associated with osteoarthritis." (PMID 36498562, 2022).
hip osteoarthritis (1 paper, 2024). "Furthermore, in a previous study, the SUPT3H (SPT3 Homolog, SAGA and STAGA Complex Component) gene was linked to bone and cartilage-related phenotypes, including height, bone mineral density, ossification of the posterior longitudinal ligament of the spine, and hip osteoarthritis." (PMID 39570887, 2024).
otosclerosis (1 paper, 2023). Formation of spongy bone in the labyrinth capsule which can progress toward the stapes (stapedial fixation) or anteriorly toward the cochlea leading to conductive, sensorineural, or mixed hearing loss. "However, the second-most significant variant in the SUPT3H locus (rs12204678, 6:45153962:C > T, meta-analysis p = 8.3 × 10−11, MAF = 41%, OR = 0.85 [0.81–0.9]) was included in EstBB and was associated with otosclerosis at nominal significance (p = 0.029, OR = 0.90 [0.86-0.95])." (PMID 36653343, 2023). "Otosclerosis colocalized genetically with the expression of BANF1, MARK3 and SUPT3H in the highest number of tissues (14, 8 and 6, respectively), while the highest causal posterior probability was observed for TELO2 (9.5%), ZNRD2 (6.3%), EHBP1L1 (6.0%)." (PMID 36653343, 2023).
cancer (4 papers, 2020 to 2022). A tumor composed of atypical neoplastic, often pleomorphic cells that invade other tissues. "SUPT3H was involved in the C-MYC pathway and transcriptional misregulation in the cancer pathway." (PMID 33029258, 2020). "For the positive–negative subjects (screening), 3 CNAs were detected in BC genes (ACVR2A, CUL3 and PIK3R1), and 5 SNPs were identified in 6 non-BC cancer genes (SNIP1, TBC1D10B, PANK1, PRKCA and RUNX2; SUPT3H)." (PMID 35589867, 2022).
SUPT3H also shares sentences with these, for which no sentence is quoted: knee osteoarthritis (1 paper); Stroke (1).